ACOX1 (acyl-CoA oxidase 1)
Diseases named in the same sentence as ACOX1 in open-access papers (continued):
Sharing a sentence is not in itself a finding about the gene and the disease.
steatosis (29 papers, 2009 to 2024). Increased lipid within the cytoplasm of cells. "For example, Acox1-deficient mice and mice with hepatocyte-selective elimination of peroxisomes both exhibit spontaneous steatosis, steatohepatitis and the development of HCC." (PMID 34572415, 2021). "It is recognized that this protein plays an important role in the NAFLD, as ACOX1-deficient mice have shown spontaneous steatosis and steatohepatitis, as well as the spontaneous development of hepatocellular carcinoma (HCC)." (PMID 33114278, 2020). "Whole body Acox1 null mice and Acox1Lampe1 mice, which features a point mutation rendering the Acox1 gene inactive, spontaneously develop steatosis and steatohepatitis." (PMID 31921154, 2019). "Differential expression of ACOX1 can cause perioral lipid accumulation on top of the initially homogeneous steatosis." (PMID 29310583, 2018). "The genes we identified as steatosis-associated by the network analysis, such as ACOX1, SCD, PPARγ, CFD and CIDEC were re-discovered by the regression analysis." (PMID 19680557, 2009). "Indeed, compound homozygous PPARα−/−, Acox1−/− mice lack increased peroxisomal proliferation and exhibit reduced steatosis and liver cell proliferation, thus verifying the essential role of PPARα in the pathogenesis of Acox1-deficient mice." (PMID 21760938, 2011). "Other studies have shown that inhibition of ACOX-1 or an abnormal ACOX-1 gene can increase steatosis." (PMID 37664863, 2023). "Acyl-CoA oxidase-1 (ACOX-1) is an important rate-limiting enzyme in the β-oxidation pathway, and activation of ACOX-1 effectively attenuated ethanol-induced hepatocyte steatosis." (PMID 37143126, 2023). "A study investigating NAFLD progression utilized a HFD and an ACOX1 KO mouse model to investigate the disadvantageous role of ACOX1 during the development of steatosis." (PMID 35805129, 2022). "Mechanistically, H2S increases PPAR expression and activates ACOX1, promoting beta-oxidation and the prevention of steatosis." (PMID 35805129, 2022). "Genes involved in steatosis (Cd36, Lpl), hepatoxicity (Avpr1a, Pla2g12a), necrosis (Serpine1), fatty acid metabolism (Acox1, Cpt1b, Cyp4a10, Ehhadh), lipid transport (Apoa1), and PPAR transcription factors (Pparδ) were altered with PFHpS exposure compared to vehicle-exposed animals." (PMID 39066581, 2024). "MPEP administration is able to almost double the expression of PPARα in our model of steatosis, and the increase in the mRNA expression of its target gene Acox1 confirm our hypothesis." (PMID 37047048, 2023). "Interestingly, ACOX1 staining was weaker in the steatotic area than in the non-steatotic area, suggesting that steatosis is associated with the impaired peroxisomal fatty acid β-oxidation." (PMID 38790950, 2024). "However, taking into account the known role of inflammation in the development of steatosis, protection given by nordihydroguaiaretate-induced ACOX1 against steatosis might result from anti-inflammatory properties of ACOX1." (PMID 29765501, 2018). "Consistent with the development of steatosis in the HFD group, important upstream regulators involved in lipid catabolism (peroxisomal acyl-CoA oxidase 1 (ACOX1), AMP kinase (AMPK) and mitochondrial biogenesis (PPARGC1a) were all inactivated with HFD." (PMID 35782914, 2022). "Our results showed that LZG treatment obviously increased the expression of EHHADH, ACOX1, and CPT1 in the liver tissues of NAFLD mice and AML12 cells with steatosis." (PMID 35035496, 2022). "Further, they have demonstrated that this improvement in steatosis involves an increased expression of transcriptional factor PPAR-α and two rate limiting enzymes, namely, acyl-CoA oxidase-1 (ACOX1) and carnitine palmitoyltranferase-1 (CPT1), which are critical to mitochondrial β-oxidation." (PMID 34944593, 2021).
steatosis (continued). "Both IHC analysis and western blot assays showed the proteins of CYP7A1, PGC-1α, PPARα, CPT1A and ACOX1 were decreased in livers tissues from patients with steatosis when compared with ones without steatosis." (PMID 29022907, 2017). "In this study, the patients with steatosis had lower levels of PPARα, ACOX1 and CPT1A than the ones without steatosis." (PMID 29022907, 2017).
hepatocellular carcinoma (15 papers, 2010 to 2025). A malignant tumor that arises from hepatocytes. "A SIRT5 deficiency in hepatocellular carcinoma (HCC) increases oxidative DNA damage by elevating ACOX1-mediated H2O2 production." (PMID 33117804, 2020). "For instance, SIRT5 mediates the desuccinylation of ACOX1, decreasing its activity in hepatocellular carcinoma development." (PMID 40243486, 2025). "Peroxisome acyl-CoA oxidase 1 (ACOX1) is the primary catalase enzyme in the peroxisomal β-oxidation pathway, the dysfunctioning of which leads to abnormal lipid metabolism and hepatocellular carcinoma, and potentially results in metabolic disorders." (PMID 40244197, 2025). "Knockout of ACOX1 promotes hepatocellular carcinoma in mice, and overexpression of ACOX1 inhibits oral cancer progression." (PMID 36878899, 2023). "In a separate investigation, ACOX1 knockout mice demonstrated hepatic metabolic disturbances that precipitated the onset of steatohepatitis, hepatocellular regeneration, spontaneous peroxisome proliferation, and hepatocellular carcinomas." (PMID 40943222, 2025). "In addition, SIRT5 regulates the activity of ACOX1 to counteract oxidative stress and is expressed less in hepatocellular carcinoma." (PMID 38585644, 2024). "In hepatocellular carcinoma (HCC), SIRT5 deficiency leads to increased succinylation and activity of Acyl-CoA Oxidase 1 (ACOX1), which is directly associated with oxidative stress and DNA damage responses in HCC." (PMID 40463370, 2025). "Some studies have shown that ACOX1 activity increasing due to SIRT5 expression downregulated in primary hepatocellular carcinoma cancer results in poor HCC survival." (PMID 37724116, 2023). "Besides, the ACOX1-induction of ROS production was demonstrated to be involved in oxidative DNA damage and the progression of hepatocellular carcinoma (HCC)." (PMID 35740025, 2022).
breast carcinoma (11 papers, 2015 to 2026). "Moreover, a decrease in lipid metabolism genes (e.g., Acly (ATP citrate lyase), Scd1, Acox1 (Acyl-CoA oxidase 1)) and an increase in cell cycle/DNA-damage-response genes (e.g., Brca1 (Breast Cancer 1), Bax (Bcl-2-associated X protein)) were observed." (PMID 39941720, 2025). "Higher expression of ACOX1 is reported in both human epidermal growth factor receptor 2 (HER2) and estrogen receptor (ER) positive breast cancers and has been associated with poor survival." (PMID 33931671, 2021). "The expression of ACOX1 is different according to the location of metastasis, and the lowest expression is in the liver metastasis of breast cancer." (PMID 29262657, 2017). "Results showed that four acyl-CoA synthetases—GCDH, ACSS2, ACOX1, and ACOX3—were significantly down-regulated in breast cancer cells, with ACSS2 showing the most pronounced reduction." (PMID 41544165, 2026). "We also found the association between expression of lipid metabolism-related proteins and poor prognosis in the breast cancer subtypes: HSL negativity and acyl-CoA oxidase 1 positivity in invasive breast cancer, and FABP4 positivity and CPT-1 positivity in the TNBC subgroup." (PMID 28124996, 2017).
X-linked adrenoleukodystrophy (11 papers, 2017 to 2025). X-linked adrenoleukodystrophy (X-ALD) is a peroxisomal disorder resulting in cerebral demyelination, axonal dysfunction in the spinal cord leading to spastic paraplegia, adrenal insufficiency and in some cases testicular insufficiency. "The accumulation of VLCFA represents a major biochemical marker of peroxisomal disorders, including X-linked adrenoleukodystrophy, Zellweger spectrum disorders, and ACOX1 deficiency." (PMID 38357503, 2024). "In humans, mutations in the ACOX1 gene may cause pseudo-neo-natal adrenoleukodystrophy, a disease that causes the accumulation of long-chain fatty acids, resulting in the demyelination and impairment of nervous signal transmission." (PMID 33260884, 2020). "These disturbances cause an imbalance in the regulation of intracellular Ca2+ and a notable decrease in the membrane potential of mitochondria in oligodendrocytes, particularly in individuals who have X-linked adrenoleukodystrophy (X-ALD) and ACOX1 deficiency." (PMID 37762279, 2023). "PEDs affecting the β-oxidation of VLCFAs are X-linked adrenoleukodystrophy (ALD), ACOX1-, DBP-, and Acyl-CoA binding domain containing protein 5 (ACBD5) deficiency." (PMID 28849344, 2018). "Zellweger syndrome, a disease characterized by abnormal peroxisome lipid metabolism presenting with deficiency of ACOX1 function, D-bifunctional protein (D-BP) and X-linked adrenoleukodystrophy (X-ALD)." (PMID 28257516, 2017). "The final aim was to gain insight into the pathogenesis of peroxisomal leukodystrophies such as X-linked adrenoleukodystrophy (X-ALD, MIM 300100) and acyl-CoA oxidase 1 (ACOX1) deficiency (MIM 264470)." (PMID 38164407, 2023).
Insulin resistance (10 papers, 2010 to 2026). Increased resistance towards insulin, that is, diminished effectiveness of insulin in reducing blood glucose levels. "Insulin resistance induces hepatic fatty acid oxidation and ACOX1 upregulation, elevating H2O2 production that exacerbates oxidative stress." (PMID 40686867, 2025). "ACOX1 expression was shown to be up-regulated after phellinus linteus treatment, reducing blood glucose levels and improving insulin resistance in diabetic mice." (PMID 35406730, 2022). "Our studies at the protein level have identified that one of the effector proteins of the insulin resistance pathway, GLUT4, has a direct relation with proteins of the fatty acids metabolism (HADH1 and ACOX1) a key pathway of the ketogenic diet." (PMID 21143928, 2010). "Based on the attenuation of fat accumulation in BAT and liver and the improvement of insulin resistance, we investigated the mtDNA copy number and the expression of lipid β-oxidation proteins in BAT, including PPARα, ACOX1, CPT1, and lipolysis proteins such as ATGL in BAT." (PMID 38576483, 2024). "In the present study, no changes in the expression of Cpt1 or Acox1 in the liver suggest that fatty acid oxidation was not enhanced in PR8 virus-infected mice despite insulin resistance." (PMID 32616893, 2020).
colorectal cancer (9 papers, 2019 to 2024). A primary or metastatic malignant neoplasm that affects the colon or rectum. "ACOX1 has been reported to regulate cancer development and its dysfunction is linked to hepatocarcinogenesis and migration and invasion of colorectal cancer cells." (PMID 30819200, 2019). "However, the role of metabolic reprogramming caused by dysregulation of the metabolic enzyme ACOX1’s post-translational modification in colorectal cancer (CRC) remains elusive." (PMID 36878899, 2023). "We identified that metabolic enzyme acyl-CoA oxidase 1 (ACOX1) suppresses colorectal cancer (CRC) progression by regulating palmitic acid (PA) reprogramming." (PMID 36878899, 2023). "Our results revealed that the high expression of ACOX1 had poorer prognosis in colorectal cancer." (PMID 36147494, 2022). "In addition, miR-15b-5p could also mediate colorectal cancer invasion and migration by targeting ACOX1." (PMID 37745305, 2023). "Our study meticulously utilized single-cell sequencing to pinpoint ACOX1 and CPT2 as pivotal oncogenes in the nucleotide metabolism of colorectal cancer." (PMID 38594466, 2024). "We evaluated the expression of ACOX1 and CPT2 in 80 pairs of colorectal cancer tissues and adjacent normal tissues using IHC methods." (PMID 38594466, 2024). "The inhibitor of ACOX1 is SIRT1, which has been proved to prevent oxidative damage and is downregulated in liver cancerr, suppresses colorectal cancer metastasis by transcriptional repression of miR-15b-5p44." (PMID 33767290, 2021). "Acyl-CoA oxidase 1 (ACOX1) is a key enzyme of the fatty acid oxidation pathway and its overexpression alleviates the migration and invasion of colorectal cancer." (PMID 32547948, 2020). "Together, these findings suggest that ACOX1 and CPT2 are oncogenes for colorectal cancer." (PMID 38594466, 2024).
liver cancer (9 papers, 2016 to 2025). An epithelial or non-epithelial malignant neoplasm that arises from the liver. "H2O2 accumulation that was accompanied by ACOX1-mediated fatty acid oxidation and the subsequent increase in oxidative stress have been implicated in the development of liver cancer in rodents." (PMID 32674458, 2020). "Downregulated genes in G1 condition were mainly associated with ovarian cancer tumors and xenografts down (dn), ELAVL1 targets up, liver cancer ciprofibrate up, liver cancer E2F1 up, liver cancer ACOX1 up, and SATB1 targets dn." (PMID 41479593, 2025). "The lysine deacetylase sirtuin 5 (SIRT5), which resides in peroxisomes, was shown to desuccinylate, and thus, inhibit ACOX1 activity in liver cancer cells." (PMID 32674458, 2020). "ACBD1 has also been associated with ACOX1 in a genome-wide transcript profiling study in which ACOX1 gene expression was downregulated following ACBD1 knockdown in a human liver cancer cell line." (PMID 32044385, 2020). "The gene set LEE_LIVER_CANCER_ACOX1_UP, which is composed of the up-regulated genes in mouse liver cancer after overexpression of ACOX1, accounted for the largest number of ER-MRTPs." (PMID 26972162, 2016). "For example, ACOX1 knockout contributed to liver cancer progression." (PMID 34124063, 2021). "The tumor-promoting function of ACOX1 upregulation was also observed in human liver cancer." (PMID 32674458, 2020). "In rodents, abnormal upregulation of ACOX1 by PPAR activation stimulates hepatic FAO and the accumulation of H2O2, leading to excess energy burning in the liver and contributing to the development of liver cancer." (PMID 36750554, 2023). "Abnormal upregulation of ACOX1 by PPAR activation was reported to stimulate hepatic fatty acid oxidation, resulting in excess energy burning in the liver and contributing to the development of liver cancer in rodents." (PMID 37724116, 2023).
diabetes (7 papers, 2010 to 2025). "From the 33 seed proteins establishing direct relationships with diabetes proteins we find 3 (ACAT1, ACOX1 and HADH1) from the central routes of ketosis, synthesis and degradation of ketone bodies and lipid metabolism." (PMID 21143928, 2010). "Key role of ACOX1 in biosyntheses of eicosanoids (E series) and docosanoids (D series) further yielding specialized proresolving mediators (SPM) (resolvins, neuroprotectins, and maresins) is stressed along with preserved or increased ACOX1 activity in models of diabetes and metabolic syndromes." (PMID 29765501, 2018). "Neither linagliptin nor empagliflozin affected the expression of PPAR-α and ACOX1, both genes involved in β-oxidation (fatty acid oxidation), in NASH mice with diabetes." (PMID 27462372, 2016). "However, a combined analysis demonstrated significant variability in relative ACOX1 abundance by ANOVA (p < 0.05), and a non-significant increase in Max samples compared to Min samples in patients with diabetes (p = 0.07) as demonstrated by western blot analysis." (PMID 35783870, 2022).
hyperlipidemia (7 papers, 2021 to 2025). "Genes related to the PPAR pathway and lipid peroxidation were significantly (P < 0.05) upregulated (PPARγ) or downregulated (PPARα, CPT1A, ACOX1) in the liver of hyperlipidemia group." (PMID 41144456, 2025). "alkaloids (10–80 mg/kg, 8 days, PO) reduced hyperlipidemia by activating Acox1 and Cpt1a genes in mice fed with HFD." (PMID 37396948, 2023).
peroxisomal biogenesis disorders (7 papers, 2012 to 2024). "In humans, ACOX1 deficiency causes impaired peroxisomal β-oxidation, producing a rare neuroinflammatory and neurodegenerative peroxisomal disease, pseudoneonatal adrenoleukodystrophy." (PMID 37724116, 2023). "There are other peroxisomal disorders that present with MRI abnormalities resembling X-ALD, in particular peroxisomal biogenesis disorders and ACOX1 or DBP deficiency with late onset of symptom." (PMID 22889154, 2012).
atherosclerosis (6 papers, 2018 to 2025). A disease characterized by the build-up of fatty material and calcium deposition in the arterial wall resulting in partial or complete occlusion of the arterial lumen. "Conversely, elevated ACOX1 expression in macrophages promotes pro-inflammatory phenotypes in type 1 diabetes, accelerating atherosclerosis progression." (PMID 40686867, 2025). "Lutein plays a regulator role in gene expression and is involved in oxidative stress and the lipid metabolism of ACOX1, thereby mitigating atherosclerosis progression." (PMID 36299582, 2022).
melanoma (6 papers, 2021 to 2025). A malignant, usually aggressive tumor composed of atypical, neoplastic melanocytes. "In addition, a study found that peroxisomal FAO (pFAO) in BRAF-mutated melanoma persister cells was up-regulated through the PPARα-PGC1α-ACOX1 axis, and the use of pFAO inhibitors combined with BRAF/MEK inhibitors to treat melanoma delayed the emergence of resistance to targeted therapy." (PMID 40514365, 2025). "Another study identified the peroxisomal enzyme ACOX1, a downstream target of PPARα, as a mediator of drug tolerance generally in melanoma persister cells." (PMID 37616051, 2023). "In melanoma, ACOX1-mediated fatty acid oxidation is involved in tumor resistance to BRAF/MEK inhibitors." (PMID 36177002, 2022).
Zellweger syndrome (6 papers, 2019 to 2025). "Like ACOX1 deficiency, the clinical presentation of severely affected patients resembles that of Zellweger syndrome, including similar ocular symptoms." (PMID 33921065, 2021). "Severely affected ACOX1 deficiency patients are indistinguishable from those suffering from Zellweger syndrome." (PMID 33921065, 2021).
lipid metabolism disorders (5 papers, 2024 to 2025). "Specifically, LLPK intervenes in biological processes such as lipogenesis, fatty acid oxidation, and fatty acid transport in mice livers by regulating the expression of key downstream factors of PPARα (Scd1, Acox1, Acaa1b, Slc27a1, Acsl1, and Ehhadh), thus improving lipid metabolic disorders." (PMID 40431433, 2025). "CIH mainly affected the transcription levels of the PPARγ, ACOX1, and UCP2 genes and further aggravated the HFD‐induced lipid metabolism disorders." (PMID 39229924, 2024).